SBSN (suprabasin)
Synonyms: UNQ698; HLAR698
Tractability: Antibody: UniProt places it where antibodies can reach, with medium confidence; UniProt predicts a signal peptide or a membrane-spanning region; its Gene Ontology location is reachable by antibodies, with medium confidence.
Gene: Protein-coding gene on chromosome 19 (35,523,367 to 35,528,351, reverse strand). Ensembl gene ENSG00000189001.
Subcellular location: Secreted
Subcellular location (Human Protein Atlas): Vesicles; Predicted to be secreted
Pathways (Reactome):
Developmental Biology: Differentiation of Keratinocytes in Interfollicular Epidermis in Mammalian Skin
Gene Ontology:
Cellular component: extracellular exosome; extracellular region
Genetic constraint (gnomAD): Loss-of-function variants: 33 observed, 41.41 expected, observed/expected ratio (o/e) 0.8, 90% interval 0.6 to 1.07. The upper end of that interval is the gene's LOEUF score, 1.07, which puts it in group 4 of 6, group 1 being the genes least tolerant of losing a copy. Missense variants: 646 observed, 742.1 expected, observed/expected ratio (o/e) 0.87, 90% interval 0.81 to 0.93. Synonymous variants: 276 observed, 295.01 expected, observed/expected ratio (o/e) 0.94, 90% interval 0.85 to 1.03.
Homologues: Orthologues: chimpanzee SBSN (95% identical), dog SBSN (72% identical), rabbit SBSN (69% identical), pig SBSN (66% identical), guinea pig SBSN (66% identical), rat Sbsn (63% identical), mouse Sbsn (57% identical), macaque SBSN (56% identical).
Diseases named in the same sentence as SBSN in open-access papers:
SBSN is named in the same sentence as 21 diseases in open-access papers, as found by Europe PMC text mining. Sharing a sentence is not in itself a finding about the gene and the disease. The quoted sentences say what the papers report.
esophageal squamous cell carcinoma (4 papers, 2018 to 2025). Esophageal squamous cell carcinoma (ESCC) is a type of esophageal carcinoma (EC) that can affect any part of the esophagus, but is usually located in the upper or middle third. "For example, SBSN expression is abnormally regulated in esophageal squamous cell carcinoma (ESCC), salivary adenoid cystic carcinoma (ACC), and NSCLC." (PMID 35222534, 2022). "Besides, previous studies suggested that suprabasin (SBSN) plays an important oncogenic role in promoting proliferation and tumorigenesis of esophageal squamous cell carcinoma." (PMID 29301256, 2018).
glioblastoma (4 papers, 2019 to 2022). The most malignant astrocytic tumor (WHO grade IV). "In malignant brain tumors, SBSN upregulation is associated with poor prognosis for patients with glioblastoma multiforme." (PMID 35222534, 2022). "Suprabasin has been implicated as an oncoprotein in highly invasive glioblastoma and esophageal cancer." (PMID 34968392, 2021). "The association of SBSN expression with poor prognosis of patients suffering from oesophageal carcinoma, glioblastoma multiforme, and myelodysplastic syndromes suggests that SBSN may play a role in human tumourigenesis." (PMID 33477529, 2021). "Recent reports indicate SBSN expression in human malignancies such as glioblastoma or lung cancer." (PMID 30919591, 2019).
esophageal cancer (3 papers, 2018 to 2021). A primary or metastatic malignant neoplasm involving the esophagus. "SBSN is shown to promote‐catenin signaling in human esophagus cancer via unknown mechanisms and its expression is a marker of colon cancer tumor endothelial cells, implicating that SBSN aberrant expression in both tumor cells and tumor‐affected healthy cells is associated with cancer malignancy." (PMID 32696549, 2020).
lung carcinoma (3 papers, 2012 to 2022). "Suprabasin (SBSN) is an oncogene and biomarker in several cancers such as lung carcinoma, salivary adenoid cystic carcinoma, and myelodysplastic syndromes (MDS)." (PMID 35216190, 2022). "We have reported previously that suprabasin (SBSN), whose expression is restricted to the epidermis, is epigenetically derepressed in lung cancer." (PMID 22792300, 2012). "We have demonstrated earlier that the non-CTA gene suprabasin (SBSN), which is normally expressed only in the suprabasal layer of epidermis, was specifically demethylated at its CpG island and subsequently expressed in lung cancer tissues." (PMID 22792300, 2012).
myelodysplastic syndrome (3 papers, 2020 to 2022). A clonal hematopoietic disorder characterized by dysplasia and ineffective hematopoiesis in one or more of the hematopoietic cell lines. "Therefore, SBSN is considered an oncogene and is a proposed biomarker in a couple of diseases, lung carcinoma and myelodysplastic syndromes (MDS)." (PMID 33477529, 2021). "Aberrantly expressed suprabasin (SBSN) is a novel biomarker in myelodysplastic syndrome (MDS) patients." (PMID 32696549, 2020).
ovarian carcinoma (2 papers, 2019). A malignant neoplasm originating from the surface ovarian epithelium. "Altogether, SBSN is expressed in fully developed human malignant lesions of colorectal and ovarian carcinomas." (PMID 30919591, 2019). "Additionally, proteins namely VASP, coronin‐1A, stathmin, and suprabasin were confidently identified in ovarian chemotherapy subjects, possibly in response to combined paclitaxel and carboplatin drug therapy to ovarian cancer." (PMID 32123828, 2019).
infertile (1 paper, 2022). "Finally, six proteins were found to be unique in the infertile group; these were neuroblast differentiation-associated protein (AHNAK), isoaspartyl peptidase/L-asparaginase (ASRGL1), UMP-CMP kinase (CMPK1), phosphoglucomutase-1 (PGM1), cornulin (CRNN), and suprabasin (SBSN)." (PMID 35719135, 2022).
lung squamous cell carcinoma (1 paper, 2019). "Intriguingly, ectopic expression of SBSN in some lung squamous cell carcinoma cell lines and normal lung fibroblasts is associated with growth advantage." (PMID 30919591, 2019).
lymph node metastasis (1 paper, 2022). "The SBSN protein expression level (2.71 ± .49 vs. 1.19 ± .20) and high-positive expression rate (18.52 vs. 0%) were significantly higher (p < .05) in the lymph node metastasis group than in the non-metastasis group, respectively." (PMID 35222534, 2022).
neuropathy (1 paper, 2024). A disorder affecting the nervous system that manifests with pain, tingling, numbness, and/or muscle weakness. "Specific genes increased in patients withoutlinezolid-associated neuropathy included ATG4C, BAX, and IGF1, while patients onlinezolid who suffered from neuropathy had an increase in AURKB, CASP3, CASP8, CDK1,CDKN1B, CEBPB, NADSYN1, NRF1, GPX7, and SBSN." (PMID 38939039, 2024).
psoriasis (1 paper, 2023). An autoimmune condition characterized by red, well-delineated plaques with silvery scales that are usually on the extensor surfaces and scalp. "Finally, suprabasin, an epithelial pro-inflammatory peptide, has also been indicated as possible regulator of mast cell activation via TLR4 leading to an increase in the inflammatory response, as demonstrated in psoriasis." (PMID 37834061, 2023).
secondary progressive MS (1 paper, 2026). "CSF BSN levels were higher in both relapsing and PPMS compared with controls, whereas sBSN was elevated in secondary progressive MS (SPMS) and PPMS." (PMID 42102575, 2026).
thyroid cancer (1 paper, 2022). "This study suggests an important role for SBSN in thyroid carcinoma and the potential mechanisms by which SBSN may be involved in the processes of thyroid cancer dedifferentiation and immune regulation." (PMID 35222534, 2022).
tumor (10 papers, 2009 to 2025). "P.g. induces macrophage polarization into tumor-associated M2, upregulating gene expression of pro-tumoral molecules (suprabasin, IL-1R2, IL-18, and TGF-α) while suppressing multiple anti-tumor cytokines (TNF-β, IFN-β, TRAIL, and TNF-α) in Cal-27 cells." (PMID 40924302, 2025). "Notably, among the top scoring genes upregulated in surviving low‐adherent cell fractions was SBSN, an oncoprotein associated with tumour progression and metastasis." (PMID 30919591, 2019). "Mice inoculated with cells overexpressing suprabasin demonstrated enhanced tumor growth compared to the vector control, by enhancing Wnt/β-catenin signaling." (PMID 34968392, 2021). "The overexpression of SBSN isoform 2 promoted proliferation and anchorage-independent growth of ESCC cell lines in vitro (and normal human oesophageal epithelial cells as well) and tumour growth in vivo, whereas SBSN knockdown showed the opposite effect." (PMID 33477529, 2021). "However, in recent years, SBSN has been reported to be aberrantly expressed in certain malignancies, and inhibition of SBSN may lead to the inhibition of cancer cell proliferation, invasion, and metastasis, suggesting that SBSN may be associated with tumor progression." (PMID 35222534, 2022). "In addition, several studies have shown that SBSN expression in tumors is regulated by several signaling pathways that affect the tumor properties." (PMID 35222534, 2022). "This suggests that SBSN may be a therapeutic target whose inhibition may promote anti-tumor immune response." (PMID 35222534, 2022). "SBSN, ZNF-711 and G6PD have not previously been associated with tumor specific expression or carcinogenesis." (PMID 19997593, 2009). "SBSN methylation levels were not correlated with gender, age, primary site, smoking history, tumor (T) stage, nodal (N) stage, presence or absence of metastasis (M stage) at diagnosis, perineural invasion, surgical margin status, or development of local recurrence or distant metastasis." (PMID 23144906, 2012).
cancer (9 papers, 2017 to 2024). A tumor composed of atypical neoplastic, often pleomorphic cells that invade other tissues. "The function of Suprabasin (SBSN) has long been unclear, although some studies have suggested its association with cancer and other diseases." (PMID 39765560, 2024). "SBSN was also found to be associated with several cancer signaling pathways, such as the PI3K/AKT and MAPK pathways; this result is consistent with those of previous studies." (PMID 35222534, 2022). "Among the identified proteins, we selected Suprabasin (SBSN), an oncogene previously associated with poor prognosis in different cancers." (PMID 35216190, 2022). "Since its original description in human and mouse keratinocyte differentiation, suprabasin (SBSN) has been associated with multiple diseases, including cancer." (PMID 33477529, 2021). "Changes in suprabasin expression in various diseases such as cancer and autoimmune disorders suggest that suprabasin has diverse functions." (PMID 34322491, 2021). "Notably, a skin‐specific protein suprabasin (SBSN), a recently identified oncoprotein, was among the top scoring genes upregulated in surviving low‐adherent cancer cells induced by 5‐azacytidine or irradiation." (PMID 30919591, 2019). "Finally, within the list of upregulated genes in the UCHL1 KD we also found several cancer-associated genes such as SERPINB4, FGF21, NUPR1, SBSN, GDF1, HMOX1, or SOCS2, which suggested the activation of potential compensatory mechanisms in these KDs cells." (PMID 28472177, 2017). "Interestingly, SBSN expression was also significantly enriched in several cancer immunity-related pathways, such as the chemokine pathway, the cytokine and its receptor interaction pathway, and the T-cell receptor signaling pathway, which are usually involved in tumorigenic processes." (PMID 35222534, 2022).
SBSN also shares sentences with these, for which no sentence is quoted: endometrial cancer (2 papers); Chorea (1); immune disorders (1); malignant brain tumors (1); thrombosis (1); transverse myelitis (1).